MIR3121 (microRNA 3121)
Synonyms: hsa-mir-3121; mir-3121
Gene: MicroRNA gene on chromosome 1 (180,438,314 to 180,438,390, reverse strand). Ensembl gene ENSG00000265435.
Homologues: Orthologues: chimpanzee MIR3121 (100% identical).